TAF10 (TATA-box binding protein associated factor 10)
Description:
The TFIID basal transcription factor complex plays a major role in the initiation of RNA polymerase II (Pol II)-dependent transcription. TFIID recognizes and binds promoters with or without a TATA box via its subunit TBP, a TATA-box-binding protein, and promotes assembly of the pre-initiation complex (PIC). The TFIID complex consists of TBP and TBP-associated factors (TAFs), including TAF1, TAF2, TAF3, TAF4, TAF5, TAF6, TAF7, TAF8, TAF9, TAF10, TAF11, TAF12 and TAF13. TAF10 is also component of the PCAF histone acetylase complex, the TATA-binding protein-free TAF complex (TFTC) and the STAGA transcription coactivator-HAT complex. May regulate cyclin E expression (By similarity).
Synonyms: TAFII30; TAF2A; TAF2H
Tractability: Small molecule: a structure with a bound ligand is known. PROTAC: ubiquitination databases record sites on it; its protein half-life has been measured.
Gene: Protein-coding gene on chromosome 11 (6,606,294 to 6,612,539, reverse strand). Ensembl gene ENSG00000166337.
Subcellular location: Nucleus
Subcellular location (Human Protein Atlas): Nucleoplasm
Pathways (Reactome):
Gene expression (Transcription): RNA Polymerase II Pre-transcription Events; RNA Polymerase II Promoter Escape; RNA Polymerase II Transcription Initiation; RNA Polymerase II Transcription Initiation And Promoter Clearance; RNA Polymerase II Transcription Pre-Initiation And Promoter Opening
Disease: HIV Transcription Initiation; RNA Polymerase II HIV Promoter Escape; Transcription of the HIV genome
Chromatin organization: HATs acetylate histones
Metabolism of proteins: Ub-specific processing proteases
Gene Ontology:
Molecular function: enzyme binding; histone acetyltransferase activity; identical protein binding; nuclear estrogen receptor binding; protein binding; RNA polymerase binding; RNA polymerase II general transcription initiation factor activity; promoter-specific chromatin binding; DNA binding
Biological process: DNA-templated transcription initiation; mRNA transcription by RNA polymerase II; positive regulation of transcription initiation by RNA polymerase II; regulation of transcription by RNA polymerase II; RNA polymerase II preinitiation complex assembly; transcription initiation at RNA polymerase II promoter; positive regulation of DNA-templated transcription; regulation of DNA repair; regulation of DNA-templated transcription; regulation of RNA splicing; transcription by RNA polymerase II; allantois development; chromatin remodeling; embryonic placenta development; gene expression; in utero embryonic development; lateral mesodermal cell differentiation; limb development; SAGA complex assembly; somitogenesis
Cellular component: cytoplasm; nucleoplasm; nucleus; perinuclear region of cytoplasm; SAGA complex; transcription factor TFIID complex; transcription factor TFTC complex; transcription preinitiation complex
Genetic constraint (gnomAD): Loss-of-function variants: 2 observed, 15.75 expected, observed/expected ratio (o/e) 0.13, 90% interval 0.051 to 0.4. The synonymous counts are far from expectation, so gnomAD's model fits this gene poorly and the ratio says little. Missense variants: 293 observed, 273.72 expected, observed/expected ratio (o/e) 1.07, 90% interval 0.97 to 1.18. Synonymous variants: 158 observed, 120.17 expected, observed/expected ratio (o/e) 1.31, 90% interval 1.15 to 1.5.
Homologues: Orthologues: chimpanzee TAF10 (99% identical), macaque TAF10 (99% identical), rabbit TAF10 (98% identical), dog TAF10 (97% identical), pig TAF10 (97% identical), rat Taf10 (93% identical), mouse Taf10 (92% identical), guinea pig TAF10 (76% identical), tropical clawed frog taf10 (66% identical), zebrafish taf10 (56% identical), Drosophila melanogaster Taf10b (36% identical), Caenorhabditis elegans taf-10 (32% identical), and 1 more.
Diseases named in the same sentence as TAF10 in open-access papers:
TAF10 is named in the same sentence as 10 diseases in open-access papers, as found by Europe PMC text mining. Sharing a sentence is not in itself a finding about the gene and the disease. The quoted sentences say what the papers report.
breast carcinoma (1 paper, 2023). "Altogether, these findings demonstrate that TAF10 promotes the proliferation and metastasis of breast cancer cells." (PMID 36639831, 2023). "Given the correlation between TAF10 expression and the development of breast cancer, we further investigated the biological function of TAF10 in breast cancer." (PMID 36639831, 2023).
embryonic carcinoma (1 paper, 2025). "Mouse Taf10, a homolog of human TAF10, is required for G1/S phase cell cycle progression in embryonic carcinoma cells." (PMID 40846851, 2025).
liver cancer (1 paper, 2023). An epithelial or non-epithelial malignant neoplasm that arises from the liver. "First, using breast, lung and liver cancer samples collected from 30 patients at a hospital, we examined the difference in relative mRNA expression of MYC and TAF10 between adjacent non‐tumour tissues and cancer tissues." (PMID 36639831, 2023).
melanoma (1 paper, 2016). A malignant, usually aggressive tumor composed of atypical, neoplastic melanocytes. "In melanomas, TAFH RNAi induced the differential expression of TBP, TAF1, TAF2, TAF6, TAF10, and TAF12 ASVs." (PMID 27499390, 2016).
cancer (4 papers, 2015 to 2025). A tumor composed of atypical neoplastic, often pleomorphic cells that invade other tissues. "The TAF10 protein has been linked to the transcriptional activation of MYC resulting in over-expression in cancer cells." (PMID 40227817, 2025). "TAF10 AutoAbs were previously shown to be elevated in microarrays for patients with early-stage lung malignancy and high-risk lung malignancy patients." (PMID 40227817, 2025). "Z363 exerts an anti‐cancer effect on cancer cell and xenograft models by co‐regulating TAF10 and MYC." (PMID 36639831, 2023). "Transwell assays demonstrated that TAF10 overexpression in MCF7 cells increased cancer cell migration." (PMID 36639831, 2023). "In summary,these results demonstrate the anti‐cancer properties of Z363, a small molecule that is co‐regulated by TAF10 and MYC." (PMID 36639831, 2023). "Our results showed that MYC and TAF10 were significantly more highly expressed in cancer tissues than in adjacent non‐tumour tissues." (PMID 36639831, 2023). "The mRNA level of proliferation-related gene ki-67 and G1/S transition related genes, CCND1 and TAF10 was evaluated to confirm the effect of Dppa4 knockdown on cancer cell proliferation." (PMID 26063247, 2015). "Indeed, enhancement of MYC transcriptional activity by TAF10 signalling promotes cell proliferation in cancer cells." (PMID 36639831, 2023). "MYC was highly expressed in cancer tissues as was TAF10 at the protein level." (PMID 36639831, 2023). "TAF10 regulates transcription in numerous types of cancer cells." (PMID 36639831, 2023). "Co‐inhibition of TAF10 and MYC may thus serve as a novel cancer therapeutic strategy." (PMID 36639831, 2023).
tumour (1 paper, 2023). "MCF7 cells (WT, MYC KO, TAF10 KO and DKO) were injected into the flanks of BALB/c nude mice to determine whether these effects translated to a change in tumour growth." (PMID 36639831, 2023).
TAF10 also shares sentences with these, for which no sentence is quoted: colon carcinoma (2 papers); atherosclerosis (1); co-infection (1); endometrioid endometrial adenocarcinoma (1).